DRD2 (dopamine receptor D2)
Diseases named in the same sentence as DRD2 in open-access papers (continued):
Sharing a sentence is not in itself a finding about the gene and the disease.
pituitary adenomas (17 papers, 2011 to 2026). "We demonstrate that human patients or murine bearing estradiol-induction or DRD2 loss are all characterized by the presence of live intratumor bacteria in the pituitary adenoma." (PMID 41655211, 2026). "Pituitary adenoma is a tumour type known to express DRD2, and the DRD2 agonist bromocriptine is already part of the standard treatment regimen in prolactin-producing adenomas." (PMID 31478179, 2020). "In line with our data, two previous studies evaluating DRDs expression by RT-qPCR also reported lower DRD2 expression levels in SCTs compared to ACTH-negative pituitary adenomas." (PMID 32971845, 2020). "To further explore the mechanisms behind the synergistic effect of p300 activation combined with DA treatment for pituitary adenomas, we hypothesized that acetylation at H3K18/27, mediated by the p300 HAT domain, plays a critical role in regulating DRD2 transcription." (PMID 39684198, 2024).
gastric cancer (16 papers, 2014 to 2024). A primary or metastatic malignant neoplasm involving the stomach. "Moreover, upregulated expression of DA receptor D2 (DRD2) is associated with elevated malignant potential of gastric cancer and PDAC, implicating a therapeutic merit of antagonizing DRD2 in these tumors." (PMID 35954387, 2022). "used Kaplan–Meier analysis to analyse the correlation between DRD2 expression and survival duration in gastric cancer patients." (PMID 38494840, 2024). "Patients with higher expression of DRD2 had a shorter survival, and the expression of DRD2 was also negatively correlated with the prognosis of gastric cancer." (PMID 38494840, 2024). "They found that the percentage of gastric cancer patients with high DRD2 expression levels (51.2%) was higher than that with low DRD2 expression levels (39.3%)." (PMID 38494840, 2024). "Dopamine has been shown to block cell cycle progression, and activation of DRD2 by dopamine in a gastric cancer cell model has been shown to suppress cancer cell invasion." (PMID 30620005, 2019). "In addition, the DRD2 antagonist thioridazine inhibits the growth of human gastric adenocarcinoma cell line (AGS) gastric cancer cells and exerts antitumor effects." (PMID 38494840, 2024). "Overexpression of DRD2 in patients with gastric cancer had shorter survival durations, and targeting DRD2 by thioridazine significantly inhibited cell proliferation in gastric cancer and reduced cell migration via suppression of EMT related genes in liver cancer." (PMID 35372029, 2022). "On the other hand, DA pathway may inhibit angiogenesis in gastric cancer via DA receptor D2 (DRD2) on endothelial cells." (PMID 35954387, 2022). "These potential treatments are likely only relevant when cAMP signalling either drives the cancer or where it is linked to therapy resistance, as in melanomas, and where there is not overexpression of the GPCR of interest (which could indicate a different mechanism; e.g., DRD2 in gastric cancers)." (PMID 31337866, 2019). "It was reported that dopamine acting through DRD2, down regulated insulin-like growth factor-1 (IGF-1) and AKT phosphorylation, thereby inhibited gastric cancer proliferation." (PMID 33937078, 2021). "Additionally, there was a negative correlation found between the expression of DRD2 and the prognosis of gastric cancer." (PMID 39000088, 2024).
type 2 diabetes (16 papers, 2012 to 2025). "Importantly, SNPs in DRD2 are associated with chronic kidney disease in Asian Indians with type-2 diabetes, which highlights the translational potential of understanding renal D2R signaling and its implications in health and disease." (PMID 37762126, 2023). "DRD2 rs6276, rs35608204, and rs1800499 are linked to and/or associated with type 2 diabetes and may be related to a repressed chromatin state in the endocrine pancreas, which is consistent with impaired insulin secretion and glucose intolerance." (PMID 37762126, 2023).
Insulin resistance (14 papers, 2011 to 2024). Increased resistance towards insulin, that is, diminished effectiveness of insulin in reducing blood glucose levels. "DRD2 encodes dopamine receptor D2 and the binding ofdopaminergic agents such as bromocriptine to dopamine receptors is used to treatT2D symptoms including hyperglycemia, insulin resistance, free fatty acids, andTG." (PMID 39076398, 2023). "DRD1 and DRD2 gene expression in subcutaneous adipose tissue correlated positively with clinical markers of insulin resistance (e.g. HOMA-IR, insulin, and triglycerides) and central obesity in subjects without T2D." (PMID 37752366, 2024). "In previous animal studies, obese mice with reduced DRD2 activation developed insulin resistance, which was attenuated by DRD2 agonist treatment." (PMID 39425884, 2024). "Studies have demonstrated that reduced DRD2 activation is involved in development of insulin resistance in obese mice, and pharmaceutical agonism of DRD2 alleviates insulin resistance in animals." (PMID 37563671, 2023). "It has been reported that diet-induced obese mice are insulin resistance and have a reduced expression of Drd2." (PMID 26018652, 2015). "Conversely, treatment with Drd2 antagonist in diet resistant mice reduced the voluntary activity and induced insulin resistance in these mice." (PMID 26018652, 2015). "In concert, these data suggest that DRD2 activation is involved in the control of glucose metabolism and that reduced dopaminergic transmission via DRD2 contributes to the metabolic phenotype (insulin resistance) of obese animals." (PMID 21603181, 2011). "We particularly postulated that stimulation of DRD2 would ameliorate insulin resistance of DIO C57Bl6 mice, whereas DRD2 antagonism would induce insulin resistance in DR animals of the same strain." (PMID 21603181, 2011). "Fifth, blockade of central DRD2 may induce insulin resistance via modulation of autonomic nervous output to peripheral tissues (including muscle, adipose tissue, and liver)." (PMID 21603181, 2011). "Since pharmacological activation of DRD2 ameliorates insulin resistance, in various obese animal models, we hypothesized that modulation of DRD2-mediated neurotransmission could reverse the metabolic phenotypes of DIO and DR mice." (PMID 21603181, 2011). "In keeping with this hypothesis, blocking DRD2 by haloperidol induced insulin resistance in DR mice, whereas activation of DRD2 by bromocriptine tended to improve insulin sensitivity in DIO mice." (PMID 21603181, 2011). "Dopamine receptor D2 (Drd2), another FTO-downregualted gene, has been reported that its expression is reduced in the diet-induced obese companied with insulin resistance." (PMID 26018652, 2015). "In summary, activation of DRD2 tends to ameliorate the metabolic profile of DIO mice, whereas antagonism of these receptors induces insulin resistance in DR mice." (PMID 21603181, 2011).
mental disorder (14 papers, 2003 to 2025). A disease that has its basis in the disruption of mental process. "Conducted on a cohort of 221 patients with treatment-resistant mental disorders, the research focused on DRD2 and HTR2A gene variants-specifically, rs1801028, rs6314, rs7997012, and rs6311." (PMID 39934320, 2025). "DRD2 is probably a crucial gene that is associated with cognitive processes, mental disorders, and drug addiction, though the statistical evidence for its causative relationships is not persuasive enough." (PMID 36011589, 2022). "Polymorphic versions of the DRD2 gene rs1076560 located in its 6th intron are considered important factors in the genetics of mental disorders and behavior." (PMID 33171585, 2020). "Dopamine is involved in several cerebral physiological processes, and single nucleotide polymorphisms (SNP) in the dopamine D2 receptor gene (DRD2) have been associated with numerous neurological and mental disorders, including those involving alterations in cognitive and emotional processes." (PMID 29716536, 2018). "In our results, therapeutic targets or biomarkers of neurological disorder and mental disorder, such as DRD1, DRD2, DRD4, HTR2A, PRL and ADRA2A, were assigned with high scores in both mirtazapine and pramipexole." (PMID 29371651, 2018).
mood disorder (14 papers, 2014 to 2025). A cognitive disorder a disturbance in which the person's mood is hypothesized to be the main underlying feature. "DRD2 encodes the dopamine D2 receptor and is implicated in traits related to reward processing and impulse control, including substance use and mood disorders." (PMID 40340892, 2025). "The PI3K-Akt pathway is a DRD2-linked signaling pathways that has been linked to thepathogenesis of mood disorders and BDNF-mediated neuroprotection." (PMID 36566472, 2023). "Polymorphisms in ADORA2A may modulate psychomotor vigilance and sleep EEG and it has been previously noted that DRD2 variants are associated with mood disorders." (PMID 25340473, 2014). "In the cluster, particular attention was given to investigating the risk posed by dopamine receptors genes (i.e., DRD1, DRD2, DRD3, and DRD4) in the development of mood disorders." (PMID 36833279, 2023).
pancreatic cancer (14 papers, 2018 to 2024). "Diphenylbutylpiperidine is an antipsychotic drug that is an effective inhibitor of DRD2 and is efficacious in treating pancreatic cancer." (PMID 38494840, 2024). "For example, pimozide, a DRD2 inhibitor, was reported to induce cell-cycle G1 arrest and apoptosis in pancreatic cancer cells." (PMID 35461314, 2022). "Recently, Jandaghi et. al. showed significant DRD2 mRNA and protein expression with corresponding activation of the DRD2 cell signaling pathway in human pancreatic tumors." (PMID 33557912, 2021). "On the opposite, it was shown that the DRD2 pathway is activated in human pancreatic cancer and that growth of pancreatic cancer xenografts was inhibited by DRD2 antagonists in mice." (PMID 31478179, 2020). "High DRD2 expression by tumour cells was most frequently observed in pheochromocytomas (30 out of 63 samples), ovarian cancer (6 out of 12 samples) and pancreatic cancer (6 out of 12 samples)." (PMID 31478179, 2020). "Accumulating evidence has shown that simultaneous inactivation of the DRD2/3 signaling pathway can have therapeutic effects in cancer patients such as pancreatic cancer, as suggested by the anti-tumor effects of ONC201." (PMID 32867127, 2020). "It was found that the expression level of DRD2 was increased in pancreatic cancer patients and that DRD2 inhibitors could slow tumour growth by inhibiting the extracellular regulated kinase (ERK) signalling pathway." (PMID 38494840, 2024). "It was discovered that pancreatic cancer patients had higher levels of DRD2 expression and that by blocking the extracellular regulated kinase signaling pathway, DRD2 inhibitors could decrease the growth of tumors." (PMID 39000088, 2024). "Similarly, the DRD2 agonist aripiprazole has been shown to increase the sensitivity of pancreatic cancer to chemotherapy." (PMID 36428964, 2022). "In pancreatic cancer, DRD2 inhibition by pimozide resulted in anticancer activity by inducing cell death through activating the cyclic adenosine monophosphate (cAMP)/protein kinase A (PKA) pathway leading to higher calcium levels and elevated ER stress, thus inducing apoptosis." (PMID 35461314, 2022). "Furthermore, DRD2 expression in pancreatic cancer patients is increased, and DRD2-related blockers can inhibit activation of the ERK signaling pathway, thereby limiting tumor progression." (PMID 36456906, 2022). "In addition, inhibition of DRD2 by siRNA reduced cell proliferation and migration, and slowed tumor growth in xenograft pancreatic cancer mouse models by inducing apoptosis and increasing cellular stress." (PMID 33557912, 2021). "In addition, D2-like DRD2 and DRD3 are associated with the scaffold protein GIPC and it has been evidenced that GIPC induced autophagy in pancreatic cancer cells." (PMID 29786666, 2018). "This is true for pancreatic cancer, for which the overexpression of dopamine receptors, particularly DRD2, was found, although some findings suggest a greater role for DRD1 receptors, as it was established that DRD1 activation may enhance antitumor activities in pancreatic cancer." (PMID 36428628, 2022). "However, despite the presence of dopamine receptors in pancreatic cancer cell lines used, RAN was found to affect cancer cells possibly through different receptors since RAN’s impact on pancreatic cancer cells was not correlated with their expression level of DRD2." (PMID 36428628, 2022).
Alzheimer disease (13 papers, 2008 to 2025). A progressive, neurodegenerative disease characterized by loss of function and death of nerve cells in several areas of the brain leading to loss of cognitive function such as memory and language. "Using pharmacology networking to specify the targets of the identified compounds with a relationship to Alzheimer’s disease, it was possible to identify the VEGFA, AChE, and DRD2 genes as the top correlated genes to Alzheimer’s disease with 8, 8, and 6 interactions in the same order." (PMID 36557216, 2022). "It has been suggested that the dopamine receptor D2 (DRD2) be examined in relation to concussions, because it has been hypothesized to effect executive function and possibly be related to Alzheimer’s disease." (PMID 29910309, 2018). "Among the top targets identified from druggability analysis, four of them (i.e., DRD2, C4B, GABA-A-R, C5AR1) were shown in the single-nuclei sequencing data because of their clinical relevance to inflammation involved in Alzheimer’s disease." (PMID 39897171, 2024). "We reported the VEGFA, AChE, and DRD2 genes as the top correlated genes to memory disorders and Alzheimer’s disease in our gene set using a theoretical computerized chemical–biological relationship between identified metabolites from OEP extract and Alzheimer’s disease." (PMID 36557216, 2022).
diabetes (13 papers, 2012 to 2024). "Not only that, but CRHR and DRD2 gene variants are likewise correlated with the development of diabetes mellitus." (PMID 37957681, 2023). "Distribution of DRD2/ANKK1 genotype in diabetes group, ACE and PGC1A genotypes in control group (P < 0.01, 0.005, and 0.05, respectively), and all three genetic loci in the total sample (P < 0.05) was significantly different from the expectations of HWE." (PMID 26846149, 2016). "Additionally, for DRD2 functionally connected with TAAR1, the mean semantic similarity values were slightly but significantly lower in the diabetes mellitus samples compared to healthy subjects’ mucosa." (PMID 39062162, 2024).
attention deficit-hyperactivity disorder (12 papers, 2011 to 2025). A disorder characterized by a marked pattern of inattention and/or hyperactivity-impulsivity that is inconsistent with developmental level and clearly interferes with functioning in at least two settings (e.g. at home and at school). "Sex differences have been found previously in DRD2 levels, particularly in the mesocortical region, which also may explain increased predisposition of males towards dopamine related disorders such as attention deficit hyperactivity disorder (ADHD)." (PMID 39075243, 2024).
epilepsy (12 papers, 2013 to 2024). A brain disorder characterized by episodes of abnormally increased neuronal discharge resulting in transient episodes of sensory or motor neurological dysfunction, or psychic dysfunction. "Tll1, dopamine receptor D2 (Drd2) and cluster of differentiation 200 (Cd200) were selected because of their reported link to epilepsy, shared interactions and molecular functions." (PMID 33584828, 2021). "The observed increase in Drd2 expression during the early stages of epilepsy could potentially serve as a protective mechanism against neurodegeneration caused by PPS." (PMID 38676299, 2024).
post-traumatic stress disorder (12 papers, 2016 to 2025). An anxiety disorder precipitated by an experience of intense fear or horror while exposed to a traumatic (especially life-threatening) event. "The DRD2 gene 957 C > T polymorphism is associated with post-traumatic stress disorder in war veterans." (PMID 36817247, 2022). "Post-traumatic stress disorder as well as sleep dysfunction arising from chronic stress have also been linked to SNP DRD2 density and DRD2 gene polymorphisms." (PMID 34945793, 2021). "Some studies found that dopamine receptor D2 (DRD2) gene was involved in genetic susceptibility to posttraumatic stress disorder, risk factors associated with smoking and schizophrenia." (PMID 32764574, 2020). "Previous studies have suggested that the DRD2/ANKK1 rs1800497 C > T polymorphism plays a critical role in the risk of post-traumatic stress disorder (PTSD)." (PMID 37274216, 2023). "Further analyses revealed that this patient subset had high rates of post-traumatic stress disorder (PTSD), and enrichment in several distinct genetic polymorphisms associated with cellular responses to stress and DNA damage (PARP1), and in striatal dopamine processing (ANKK1, COMT, DRD2)." (PMID 28257413, 2017).
substance abuse (12 papers, 2009 to 2024). The use of a drug for a reason other than which it was intended or in a manner or in quantities other than directed. "Physiologically, dysfunction of the dopamine receptor gene DRD2 gives rise to a ‘reward deficiency syndrome’ that is associated with increased risk taking, substance abuse and eating pathology." (PMID 27658266, 2016). "The nominally significant effects of DRD2 polymorphisms on substance abuse in our sample might also relate to the association between DRD2 and impulsive self-damaging behaviors." (PMID 20205808, 2010). "A model that links striatal D2R deficits, D2 dopamine receptor (DRD2) (and ANKK1) genes, and substance abuse is the “reward deficiency syndrome” (RDS) model by Blum and Colleagues." (PMID 24065931, 2013). "The D2 dopamine receptor (DRD2) minor (A1) allele DRD2 A1 has already been linked to ADHD, Tourette's syndrome, conduct disorder and substance abuse." (PMID 19480721, 2009). "There are five dopamine receptor genes, DRD1, DRD2, DRD3, DRD4, and DRD5, which are mainly related to different risky behaviors like substance abuse and addiction." (PMID 38254998, 2024).
adenoma (11 papers, 2015 to 2024). A neoplasm arising from the epithelium. "The study found that rs7131056 in DRD2 contributes to either faster adenoma growth or less symptomatology, allowing PAs to grow larger before they are detected." (PMID 39202532, 2024).